CTBP1 (C-terminal binding protein 1)
Diseases named in the same sentence as CTBP1 in open-access papers (continued):
Sharing a sentence is not in itself a finding about the gene and the disease.
COVID-19 (1 paper, 2024). A disease caused by infection with severe acute respiratory syndrome coronavirus 2. "Both genes were also coenriched in the Notch pathway, TLE3, and NCSTN; nonetheless, CTBP1 significantly differed in the COVID-19 comparison group, whereas DTX3L was more significant in the PQ comparison group." (PMID 39301288, 2024).
dementia (1 paper, 2023). Loss of intellectual abilities interfering with an individual's social and occupational functions. "However, only six of these genes emerged to be associated with AD in a certain way: HMGB1, which is related AD dementia according to ‘Disease Ontology’; KANSL1; BAZ2B; EHMT1; SIRT1; and CTBP1, which are associated with AD according to the literature data." (PMID 37175659, 2023).
hypertrophic cardiomyopathy (1 paper, 2023). A condition in which the myocardium is hypertrophied without an obvious cause. "In our study, the CACNA2D3 and CTBP1 gene was enriched in the Cardiac muscle contraction, Hypertrophic cardiomyopathy, and Notch signaling pathway." (PMID 37828092, 2023).
idiopathic pulmonary fibrosis (1 paper, 2024). Idiopathic pulmonary fibrosis (IPF) is a nonneoplastic pulmonary disease that is characterized by the formation of scar tissue within the lungs in the absence of any known cause. "In this study, CTBP1 was found to be a novel profibrotic factor in idiopathic pulmonary fibrosis." (PMID 37138491, 2024).
microcephaly (1 paper, 2020). A congenital or acquired developmental disorder in which the circumference of the head is smaller than normal for the person's age and sex. "We identified the candidate genes PPARGC1A, CTBP1, TRIO, TERT, and CCT5 that are associated with the neuropsychomotor delay, microcephaly, and neurological alterations found in our patient." (PMID 32625234, 2020).
neurodevelopmental disabilities (1 paper, 2020). "Since the CTBP1 p.R342W mutation is associated with neurodevelopmental disabilities, we designed experiments to compare the transcriptional profiles of patient and healthy control derived neuronal cell models." (PMID 33192249, 2020). "A recurrent de novo mutation in the transcriptional corepressor CTBP1 is associated with neurodevelopmental disabilities in children." (PMID 33192249, 2020).
non-small cell lung carcinoma (1 paper, 2021). A group of at least three distinct histological types of lung cancer, including non-small cell squamous cell carcinoma, adenocarcinoma, and large cell carcinoma. "Additionally, it was shown that other pathways are involved in the mediation of CCL2 secretion and TAM recruitment, e.g., upregulation of CtBP1 promoted activation of CCL2 secretion and, as a result, infiltration of TAMs in non-small cell lung cancer (NSCLC)." (PMID 33919517, 2021).
ocular melanoma (1 paper, 2019). A melanoma that arises from the structures of the eye or ocular adnexa. "Other tumor-related genes, such as ACAT2, PIR and CTBP1, were potentially regulated by m6A modifications in ocular melanoma." (PMID 31722709, 2019).
pituitary tumor (1 paper, 2014). A benign or malignant neoplasm affecting the pituitary gland. "CtBP1 interacted with Ikaros in pituitary tumor cells, and modulated their survival in response to hypoxia." (PMID 25301737, 2014).
pulmonary fibrosis (1 paper, 2024). Chronic progressive interstitial lung disorder characterized by the replacement of the lung tissue by connective tissue, leading to progressive dyspnea, respiratory failure, or right heart failure. "Our study preliminarily demonstrated the close association between ZEB1 and CTBP1 in pulmonary fibrosis on both animal and cellular levels." (PMID 37138491, 2024). "An animal model of pulmonary fibrosis was established to analyze the effects of CTBP1 silencing on pulmonary fibrosis and lung function in mice." (PMID 37138491, 2024). "Experimental results showed that CTBP1 was highly expressed in pulmonary fibrosis cell lines." (PMID 37138491, 2024). "To further study the function of CTBP1, we constructed a mouse model of pulmonary fibrosis." (PMID 37138491, 2024). "In order to investigate whether Toosendanin can play a role in the treatment of pulmonary fibrosis through CTBP1/ZEB1, fibroblast models were established in vitro." (PMID 37138491, 2024). "In addition, we found that Toosendanin plays an inhibitory role in pulmonary fibrosis by inhibiting CTBP1/ZEB1." (PMID 37138491, 2024). "It is speculated that CTBP1/ZEB1 may be the protein target of Toosendanin playing the role of anti-pulmonary fibrosis." (PMID 37138491, 2024). "The purpose of this study was to investigate whether CTBP1 plays a role in the proliferation and activation of pulmonary fibrosis fibroblasts through ZEB1." (PMID 37138491, 2024). "It is preliminarily confirmed that CTBP1 may be involved in the occurrence and development of pulmonary fibrosis." (PMID 37138491, 2024). "Silencing CTBP1 reduced the degree of pulmonary fibrosis in mice with pulmonary fibrosis." (PMID 37138491, 2024). "However, the relationship between CTBP1 and pulmonary fibrosis is rarely reported." (PMID 37138491, 2024). "The expression of CTBP1 was detected by stimulating the cells with pulmonary fibrogenic cytokines (FCS, PDGF-BB, IGF-1, transforming growth factor –β1) to simulate the pulmonary fibrosis model." (PMID 37138491, 2024). "CTBP1 can promote the activation of lung fibroblasts and the deposition of extracellular matrix (ECM) such as collagen and fibronectin by enhancing TGF-β signaling, ultimately exacerbating the development of pulmonary fibrosis." (PMID 37138491, 2024).
Tetralogy of Fallot (1 paper, 2017). A congenital cardiac malformation comprising pulmonary stenosis, overriding aorta, ventricular septum defect, and right ventricular hypertrophy. "Our findings identify PEX5, NACA, ATXN2, CELA1, PCDHB4 and CTBP1 mutations as underlying genetic causes of isolated tetralogy of Fallot." (PMID 29291004, 2017). "Analysis using Gene Ontology /pathway, Online Mendelian Inheritance in Man, PubMed and other databases revealed that PEX5, NACA, ATXN2, CELA1, PCDHB4 and CTBP1 were associated with Tetralogy of Fallot." (PMID 29291004, 2017).
tongue cancer (1 paper, 2019). A malignant neoplasm affecting the tongue. "Early stage tongue cancer patients were significantly classified into patients with poor/good survival based on alterations in AP2M1, CTBP1, and MTFR1 all of whom were associated with prognosis in other studies." (PMID 31310629, 2019).
uterine tumours (1 paper, 2025). "The EWSR1::CTBP1 gene fusion has never previously been reported in uterine tumours, having been reported in the literature only once, in the context of a gastroblastoma." (PMID 41073540, 2025).
Wolf-Hirschhorn syndrome (1 paper, 2020). Wolf-Hirschhorn syndrome (WHS) is a developmental disorder characterized by typical craniofacial features, prenatal and postnatal growth impairment, intellectual disability, severe delayed psychomotor development, seizures, and hypotonia. "Phenotypes caused by the CTBP1 p.R342W allele partially overlap with some core phenotypes of Wolf-Hirschhorn syndrome (WHS)." (PMID 33192249, 2020).
tumor (76 papers, 2009 to 2026). "Functional analysis confirmed that ARRB1 and CTBP1/2 were associated with early tumor development, while COL1A2 and CEBPZ were involved in extracellular matrix remodeling and transcriptional regulation, respectively." (PMID 40362431, 2025). "Corroborating these results in human CD8 cells, we found that CTBP1 ablation again caused a stronger persistence phenotype after chronic stimulation with antigen-matched tumor cells." (PMID 38490212, 2024). "Research has demonstrated that CtBP1 is overexpressed in a wide range of cancers and is associated with increased tumor invasiveness and metastasis, playing a role in cancer development and progression through multiple mechanisms." (PMID 38932279, 2024). "CTBP1 is a key gene in the Notch signaling pathway and encodes a transcriptional corepressor protein that plays crucial roles in tumor development and progression." (PMID 35860803, 2022). "C-terminal binding proteins (CtBPs) encoded by the closely-related genes CTBP2 and CTBP1 mediate transcriptional repression of a number of key tumour suppressor genes." (PMID 24068937, 2013). "This latter effect is relevant in tumor progression, since Golgi fragmentation is necessary for mitotic entry, and inhibition of CtBP1/BARS causes a potent cell cycle arrest in the G2 phase followed by apoptosis (reminiscent of the effects of anti-cancer drugs)." (PMID 38711119, 2024). "Next, we tested if the loss of CTBP1 is able to mimic the effects of miR-644a on tumor metastasis." (PMID 27409664, 2016). "CTBP1 has also been reported to be associated with adenomatous polyposis coli (APC), a tumor suppressor, suggesting a role in suppressing Wnt target gene expression." (PMID 40362431, 2025). "The identification of prognostic markers through Cox regression and Lasso regression further highlighted the significant role of the risk genes BOP1, CTBP1, DSE, SRPK1, and PMSD10, which were upregulated in high mRNAsi tumor cells." (PMID 40963856, 2025). "NSCLC cells also exhibit up-regulation of CTBP1, which stimulates CCL2 secretion, contributing to tumor-associated macrophage recruitment and polarization, and promoting NSCLC progression." (PMID 41154714, 2025). "The analysis revealed that risk genes (BOP1, CTBP1, DSE, SRPK1, and PMSD10) were significantly upregulated in tumor samples, whereas the protective gene HACD4 was highly expressed in normal samples." (PMID 40963856, 2025). "By integrating both single-cell and bulk RNA-seq data, we identified six key prognostic genes (BOP1, CTBP1, DSE, PMSD10, SRPK1, and HACD4), which were associated with poor prognosis and tumor cell proliferation." (PMID 40963856, 2025). "The enhanced effector persistence allows for improved tumor control and prolonged survival in a chronic tumor-antigen-stimulation mouse model, meriting therapeutic exploration of Ctbp1 inactivation for T cell therapy." (PMID 38490212, 2024). "The transcriptional activity of CtBP1/BARS controls several genes involved in cell proliferation and tumor growth, including p16INK4a, p14ARF, Ciclin D1 and p21." (PMID 38711119, 2024). "For Marek’s disease virus (MDV), there is an interaction between the encoded protein MEQ (MDV EcoRI Q fragment) and CtBP1, which has been implicated in MDV-induced tumor formation." (PMID 38932279, 2024). "We observed 9/18 complete responses for ACT with Ctbp1-KO cells compared to 1/18 for control cells, resulting in significantly longer overall tumor-free survival." (PMID 38490212, 2024). "By repressing a broad array of tumor suppressors, CtBP1 promotes cancer cell proliferation, migration, invasion, and resistance to apoptosis." (PMID 37762332, 2023). "We show that the tumor suppressor ZBTB18 interacts with the co-factors CTBP1/2 and represses the expression of SREBP genes, involved in de novo lipogenesis." (PMID 36414381, 2023). "CTBP1, a transcriptional repressor that antagonizes tumour suppressors, is activated by NADH and in turn increases the levels of NADH in cells." (PMID 35886000, 2022).
tumor (continued). "CtBP1/2 are highly expressed in several human cancer types, with their expression level correlating to the poor prognostic outcomes and aggressive tumor characteristics." (PMID 34349099, 2021). "CTBP1 increased breast and prostate tumor growth and metastasis, in MetS mice, by modulating multiple genes and miRNAs expression implicated in the extracellular matrix (ECM), cell adhesion, and cell proliferation." (PMID 34199293, 2021). "Altogether, these results suggest that CTBP1 hyperactivation is critical for MetS effect on cancer progression and metastasis since CTBP1 depletion diminishes the detection of circulating tumor cells and the number and size of metastasis." (PMID 34199293, 2021). "The administration of CDDP also significantly decreased the tumor volumes in mice injected with CtBP1-KD or FOXM1-KD cells when compared with mice injected with MG63-R1 orMG63-R2 cells." (PMID 33391445, 2021). "For example, miR-137 functions as a tumor suppressor and it can target CtBP1 directly to inhibit EMT (epithelial-mesenchymal transition) and induce apoptosis in melanoma cells." (PMID 32140068, 2020). "CtBP1 tumour‐bearing mice were treated with sc‐202525 or Clodronate‐liposome, the tumour growth curve and growth were evaluated." (PMID 32910558, 2020). "We found that hyperactivation of CTBP1 by MeS increased the percentage of mice with lung metastases and liver neoplastic disease, which includes hepatic micometastasis and intravascular tumor cells." (PMID 29568399, 2018). "To elucidate CTBP1 and MeS effect on BrCa progression in vivo, here we analyzed expression levels of genes involved in key steps of tumor progression in xenografts generated in the MeS-like model." (PMID 29568399, 2018). "For instance, FOXP2 can interact with C-terminal binding protein 1 (CTBP1), a transcriptional corepressor that modulates and targets tumor suppressors expression, such as BAX, PTEN and p16." (PMID 30360388, 2018). "CTBP1 hyperactivation seems to be critical for MeS effect on BrCa metastasis since CTBP1 depletion completely impaired the detection of circulating tumor cells." (PMID 29568399, 2018). "Previously, we demonstrated that CTBP1 hyperactivation by MeS increased tumor growth in MDA-MB-231-derived xenografts regulating several genes and miRNAs." (PMID 29568399, 2018). "In summary, CTBP1 diminished cell adhesion and increased cell migration, both initial processes for tumor progression, in TNBC cells." (PMID 29568399, 2018). "Previously, we identified CTBP1 hyperactivation by MeS as an inductor of breast carcinogenesis and tumor growth in mice." (PMID 29568399, 2018). "In GSE4922 and GSE58644 datasets, CTBP1 levels were found to be correlated with higher tumor size and incidence of developing distant metastasis." (PMID 27409664, 2016). "In accordance with the tumor stage, patients with 20 or more positive lymph nodes had higher CTBP1 in their primary tumors suggesting a role of CTBP1 in promoting lymph node metastasis." (PMID 27409664, 2016). "Mechanistically, miR-644a directly targets the transcriptional co-repressor C-Terminal Binding Protein 1 (CTBP1) whose knock-outs by the CRISPR-Cas9 system inhibit tumor growth, metastasis, and drug resistance, mimicking the phenotypes induced by miR-644a." (PMID 27409664, 2016). "In this work we examined the role of CtBP1 in breast carcinogenesis and tumor growth using a MeS experimental model." (PMID 26933806, 2016). "Both cell lines showed efficient downregulation of CTBP1, and exhibited delayed and significantly decreased tumor growth and tumor size in nude mice." (PMID 27409664, 2016). "A significantly decreased tumor growth was observed in CtBP1 depleted xenografts compared to controls in both, HFD or CD fed mice." (PMID 26933806, 2016). "In future, it would be highly interesting to extend the analysis and perform in vivo analysis to look at effects of full length CtBP1 upon tumor growth in a nude mouse model." (PMID 19216735, 2009).
tumor (continued). "We synthesize findings from experimental studies that support CTBP1 as an oncogenic driver in specific tumor contexts, while explicitly highlighting settings in which evidence remains indirect, incomplete, or confined to locus-associated noncoding RNAs rather than CTBP1 protein itself." (PMID 41972124, 2026). "In our study, we also noted elevated levels of CTBP1, a transcriptional co-repressor that could facilitate the repression of tumor suppressors." (PMID 41463075, 2025). "To examine the functionality of Ctbp1-KO T cells, and to test our hypothesis, we determined their tumor-killing capacity and effector phenotype after 3 weeks chronic tumor-antigen stimulation in vitro." (PMID 38490212, 2024). "The reason for this situation may be that CtBP1/2 are regulated by different substances in different tumor microenvironments." (PMID 38932279, 2024). "Overall, the present study highlights the progress made by our group on the theory and rationale for the identification and validation of a selective and potent CtBP1/BARS inhibitor but also provides an important tool to define the functional role of CtBP1/BARS in tumor biology." (PMID 38711119, 2024). "Thus, CtBP1 is not only at the center of tumor metabolism and transcriptional control but also participates in a series of biochemical reactions by regulating intracellular NADH content." (PMID 38932279, 2024). "Furthermore, mice receiving Ctbp1-KO T cells showed better tumor control 20 days after viable tumor cell injection (44 days post ACT)." (PMID 38490212, 2024). "CtBP1-p300-FOXO3a transcriptional complex negatively regulates FOXO3a levels and represses the expression of the pro-apoptotic regulators Bax and Bim in human OS cells, finally promoting the tumor progression." (PMID 37284323, 2023). "Overall, these data identify CTBP1/2 as new ZBTB18 interactors in GBM cells and suggest that ZBTB18 might employ both a CTBP-dependent and a CTBP-independent mechanism to repress target genes and mediate its tumor suppressor functions." (PMID 36414381, 2023). "Notably, enhanced CtBP1 expression is associated remarkably with TNM in its advanced stage, metastasis of the lymph node, and a poor differentiation of tumour in NSCLC." (PMID 32910558, 2020). "Moreover, hsa-miR-205-5p, a known tumor suppressor miRNA, was highly upregulated in CTBP1-depleted tumors." (PMID 30931931, 2019). "CTBP1 is a transcriptional corepressor of many tumor suppressor genes." (PMID 30931931, 2019). "The ability of CtBP1/2 to alter various gene networks that regulate cellular differentiation, proliferation, and survival suggests that CtBP1/2 overexpression in adult tissue could promote both tumorigenesis and tumor progression." (PMID 29879296, 2018). "Transcriptional regulatory activity of FOXP2 may be modified by the co-factor CtBP1 (described in section 1.3.1 and 3.3.2) and this interaction may have important oncogenic consequences considering the tumor-promoting activity of CtBPs." (PMID 29725501, 2018). "All these suggest an important role of CTBP1 in tumor recurrence in chemotherapy treated patients." (PMID 27409664, 2016). "We found CTBP1 as the most promising candidate since it is an established transcriptional co-repressor which preferentially represses the transcription of tumor suppressor genes and promotes tumor growth via playing pivotal roles in tumor pathogenesis." (PMID 27409664, 2016). "Importantly, xenograft gene expression analysis determined that CtBP1 significantly increased tumor growth in mice with MeS regulating expression of genes involved in proliferation, stem cell phenotype, EMT and breast development." (PMID 26933806, 2016).